IL6 (interleukin 6)
Diseases named in the same sentence as IL6 in open-access papers (continued):
Sharing a sentence is not in itself a finding about the gene and the disease.
delirium (continued). "Accordingly, in this study, we sought to test the hypothesis that peripheral 17β-estradiol ameliorates acute delirium-like phenotypes via modulation of peripheral IL-6 using a murine model of UTI." (PMID 36380004, 2022). "Since neurons do not express the IL-6 receptor, we hypothesized that the systemic IL-6/soluble IL-6 receptor (sIL-6R) complex may induce delirium-like phenotypes via the IL-6 trans-signaling pathway as proposed in diverse neurodegenerative pathologies." (PMID 36380004, 2022). "Finally, microglia reactivation induced by peripheral IL-6 in the associated brain region, and neuroactive molecule of QUIN were found and studied using this new mouse model of postoperative delirium." (PMID 36160165, 2022). "The first major finding of this study is that delirium and/or the severity of delirium symptoms are significantly associated with the IRS/CIRS ratio, namely positively with M1 (i.e. IL-6, CXCL8 and TNF-α), Th1 and Th17 activation and T cell growth (positively), and inversely with IL-4 and sIL-1RA." (PMID 35641947, 2022). "Interestingly, it has been reported that the high blood level of IL-6 is observed in patients with delirium during hospitalization in the ICU." (PMID 36077505, 2022). "We hypothesized that systemic IL-6 inhibition would mitigate delirium-like phenotypes in a mouse model of UTI." (PMID 34711238, 2021). "The findings of this study suggest that pharmacological modulation of the IL-6 pathway may offer an opportunity to mitigate delirium, for which there are several potential advantages." (PMID 34711238, 2021). "Interleukin 6 (IL-6) has been strongly associated with the duration of delirium in non-demented patients." (PMID 35115974, 2021). "Accordingly, in this study, we sought to examine whether UTI produces symptoms that resemble delirium, and to study mechanisms by which this may occur, by characterizing the functional and structural role of IL-6 in a mouse model of UTI." (PMID 34711238, 2021). "We, therefore, set out to determine whether anesthesia/surgery causes age-dependent gut microbiota dysbiosis, changes in brain IL-6 level and mitochondrial function, leading to postoperative delirium-like behavior in mice." (PMID 31974315, 2020). "The postoperative delirium-like behavior, gut microbiota, levels of brain IL-6, PSD-95 and synaptophysin, and mitochondrial function were determined by a battery of behavioral tests, 16s rRNA sequencing, ELISA, Western blot and Seahorse XFp Extracellular Flux Analyzer." (PMID 31974315, 2020). "Among inflammatory markers, increased procalcitonin, CRP, and IL-6 were consistently reported to be associated with delirium with the exception of one study that found no increase in IL-6 levels." (PMID 31263968, 2019). "This hypothesis is supported by previous work demonstrating elevated levels of cytokines such as interleukin 6 in patients with delirium." (PMID 27544077, 2016). "In addition, several observational studies reported associations between the elevation of peripheral inflammatory biomarkers such as interleukin-6, interleukin-8, matrix metalloproteinase-9, and protein C and delirium in ICU patients." (PMID 25992641, 2015). "A study investigating Interleukin-6 (IL-6), Interleukin-8 (IL-8), and Interleukin-6 Receptor (IL-6R) genetic variations and delirium, found no polymorphisms associated with delirium." (PMID 24795632, 2014). "This is consistent with the previous reports that elderly patients who develop postoperative delirium may exhibit an elevated serum IL-6 level." (PMID 24337734, 2014). "In the present randomized trial, we studied whether FTS could prevent or reduce the occurrence of postoperative delirium as well as other complications in elderly patients with colorectal carcinoma and evaluated the role of IL-6 in postoperative delirium." (PMID 24337734, 2014). "The incidence of delirium correlates with the serum IL-6 level." (PMID 24337734, 2014).
delirium (continued). "Preliminary studies with brain tissue obtained from 9 patients with delirium was compared to 6 age-matched controls without delirium, and it was found that there was an association of human brain activity of microglia, astrocytes, and IL-6 with delirium in elderly patients." (PMID 25722876, 2014). "Higher IL-6 levels in preoperative serum in association with postoperative delirium, in the absence of such a relation in CSF, is difficult to explain." (PMID 24093540, 2013). "We found that patients with postoperative delirium have higher levels of serum IL-6, which is conform the systemic inflammatory hypothesis of delirium." (PMID 24093540, 2013). "Preoperative serum IL-6 was significantly higher in patients with postsurgical delirium (P=0.021)." (PMID 24093540, 2013). "One can speculate that increased serum IL-6 levels may be an early manifestation of an increased inflammatory reaction in patients prone to develop delirium 24 h later on average." (PMID 24093540, 2013). "IL-6 and IL-8 (the functional homologue of CXCL1 in mouse) have been associated with delirium." (PMID 23840908, 2013). "However, this timeline for development of delirium is consistent with the peak levels of inflammatory mediators in the postoperative period, such as interleukin-6 (which peaks after 24 h) and C-reactive protein (which peaks after 48 h)." (PMID 23272945, 2012). "We showed, by using a multivariate logistic regression analysis, that levels of IL-8 in inflamed patients were associated with delirium, but IL-6 was not." (PMID 22206727, 2011). "A possible reason for this discrepancy might be that we determined biomarkers directly after the first positive delirium screening, whereas it has been shown that the highest levels of IL-6 occur in the later phase of delirium." (PMID 22206727, 2011). "Furthermore IL-6, PCT, cortisol, ratio Tau/Aβ1-42, Aβ1-40, and AβN-40 were in total the 10 best, with delirium-associated biomarkers (all P < 0.10) in univariate logistic regression analysis." (PMID 22206727, 2011). "Metformin and interleukin-6 antagonists may become effective anti-delirium drugs." (PMID 38523173, 2024). "Moreover, the latest study stated that IL-6 might mediate a delirium-like phenotype in the mouse model of UTI, providing a preclinical rationale for clinical studies of IL-6 inhibitors for the treatment of delirium-induced by UTI." (PMID 39766247, 2024). "In addition, IL-6 is a reliable predictor of postoperative delirium." (PMID 39399511, 2024). "Our recent preclinical studies using murine models of delirium in mechanical ventilation and acute lung injury demonstrate a direct pathophysiological role for peripheral IL-6 in inducing delirium-like structural and functional phenotypes via the IL-6-trans-signaling pathway." (PMID 38778074, 2024). "In a mouse model of non-infectious acute lung injury, we have recently revealed that systemic IL-6 suppression reverses delirium-like neuronal alterations in the frontal cortex and hippocampus, indicating that IL-6 plays a central role in producing delirium-like structural phenotypes." (PMID 37373482, 2023). "Thus, higher postoperative serum biomarkers like S100β or IL-6 could represent a mirror of the inflammatory processes in the CNS during delirium." (PMID 37373482, 2023). "Moreover, increased concentration of IL6 in serum samples from delirium patients stimulated the hippocampal cells to produce IL12 and IL13, and treatment with an antibody against IL12 or IL13 also prevented the decreased cell proliferation and neurogenesis, and the increased apoptosis." (PMID 36195636, 2022). "However, at least one prior study in humans has found decreased systemic IL-6 with prone positioning, which may indirectly mitigate delirium-relevant neuropathology." (PMID 36405620, 2022).
delirium (continued). "Although upregulation of systemic interleukin-6 (IL-6) and other inflammatory cytokines have been reported in systemic infection models, it remains unknown whether these cytokines contribute to the pathogenesis of delirium." (PMID 34711238, 2021). "However, in another study the association between delirium and higher IL-6 plasma levels was not confirmed." (PMID 29641605, 2018). "Likewise, the association between delirium and higher IL-1, IL-6 and TNF-α plasma levels was not confirmed." (PMID 26106326, 2015). "It has been reported that opioids can stimulate IL-6 production in both animal and human studies, so anesthesia and analgesia without utilizing opioid drugs may be an important factor for reduced IL-6 levels and reduced postoperative delirium in patients managed with FTS." (PMID 24337734, 2014). "Moreover, the highest level of IL-6 was present during postoperative delirium." (PMID 24337734, 2014). "In line with this evidence, several studies in medical and surgical patients have shown that plasma levels of several inflammatory markers, particularly IL-6, and cortisol are altered before and/or during delirium supporting the aberrant stress response/neuroinflammatory hypothesis of delirium." (PMID 21994844, 2011). "The upregulation of acute inflammatory markers in our study, notably IL-6, CRP, and SAA following CPB exposure, is consistent with the neuroinflammation model of delirium." (PMID 40648974, 2025). "Hypotension also triggers inflammatory responses, releasing cytokines like IL-6 and TNF-α, contributing to delirium." (PMID 39090732, 2024). "We measured the expression of COX-2, IL-1β, IL-6, and TNF-α in the blood using ELISA on both the day of delirium onset (D1) and the 5th day after delirium onset (D5)." (PMID 38902693, 2024). "Inflammatory markers such as interleukin-1B (IL-1B), interleukin-6 (IL-6), and tumor necrosis factor-a (TNF-a) have been observed to be elevated in patients with delirium." (PMID 38263028, 2024). "We have summarized the 13 most studied proteins (IL-6, CRP, IL-8, S100B, IL-10, TNF-a, IL-1b, Cortisol, MCP-1, GFAP, IGF-1, IL-1ra and NFL) about delirium." (PMID 39700095, 2024). "We previously reported that the onset and severity of delirium are significantly correlated with IRS activation, including increased M1 (with IL-6, IL-8, and TNF-α), Th1, Th17, and T cell growth profiles." (PMID 38379706, 2024). "Secondary endpoints were intraoperative hemodynamic instability, pain score, fentanyl consumption and delirium in the post-anesthesia care unit (PACU), and perioperative changes in interleukin-6 and natural killer (NK) cell activity." (PMID 36803564, 2023). "In septic encephalopathy, coma patients (n = 18) displayed higher IL-6, TNF-α and IL-12 plasma concentrations than delirium patients (n = 64)." (PMID 37744876, 2023). "A few proteins (IL-8, LTBR, TNF-R2 postoperatively; IL-8, IL-6, LIF, ASGR1 by pre- to postoperative change) and 12 networks were common to delirium in both age groups." (PMID 37156856, 2023). "Ferritin concentration, hemoglobin, red and white cell counts, serum iron, interleukin 6 (IL-6) concentrations and hospitalization, ICU admission, delirium, and mortality." (PMID 36440432, 2022). "Overall, these findings are consistent with decreased activation of the IL-6 trans-signaling pathway via a reduction in plasma and cortical IL-6, which we have previously hypothesized contributes to neuronal injury/neurodegeneration and ultimately delirium-like behaviors." (PMID 36380004, 2022). "The results indicated that proinflammatory IL-6 persisted highly in the small intestine, blood, and BLA in I/R-induce delirium-like mice." (PMID 36160165, 2022). "Our study provided new insights into the neurological basis of postoperative delirium and highlighted Il-6, microglia, and QUIN as targets for the treatment of postoperative delirium." (PMID 36160165, 2022).
delirium (continued). "Given that these pro-inflammatory cytokines, especially IL-6, have also been demonstrated to be elevated in AKI, similar mechanisms for delirium in AKI are likely, but remain to be proven." (PMID 36030220, 2022). "The relationship between higher cytokines levels (IL-6), C-reactive protein (CRP) and delirium was previously observed in the population of ICU patients and individuals after non-cardiac surgery." (PMID 35175161, 2022). "Recent work correlated markers of systemic inflammation and those of astrocyte and glial cell activation (IL-6, IL-8, IL-10, TNF-α, C-reactive protein and S-100β levels) with longer duration of delirium, more severe delirium and higher in-hospital mortality." (PMID 32443606, 2020). "Five proteins (CHI3L1, IL6, SFRP2, PMP2, and RTN4R) differed in serum in patients with postoperative delirium compared to baseline with corrected p < 0.01 and 11 at p < 0.05." (PMID 30367354, 2018). "In patients with delirium markers of microglial activity (HLA-DR and CD 68), astrocyte activity (GFAP) and IL-6 were increased." (PMID 25943983, 2015). "The lower incidence of delirium in the FTS group is likely attributable to the reduced systemic stress and inflammatory response mediated by IL-6." (PMID 24337734, 2014). "The correlation between the levels of S100B and the proinflammatory cytokines IL6 and IL8 in the patients in this study can be seen as an indication that the neuroinflammatory system is related to possible cerebral damage due to delirium." (PMID 19473521, 2009). "Other studies in the literature, in particular, reported that elevated IL-6 and IL-8 serum values contribute to organic delirium onset in the elderly and predict negative outcomes in this population." (PMID 40142633, 2025). "Additionally, common cytokine imbalances in AID patients, especially the elevation of pro-inflammatory factors such as IL-1β, IL-6, TNF-α, have been found to be closely related to the occurrence of delirium." (PMID 40740958, 2025). "Patients who developed delirium exhibited profoundly elevated preoperative plasma IL-6 levels compared to their non-delirious counterparts." (PMID 41229511, 2025). "The study did not include other relevant biomarkers of systemic or neuroinflammation (e.g., interleukin-6, TNF-α, or S100B protein), which could have provided a broader mechanistic understanding of the inflammatory contribution to delirium." (PMID 41303282, 2025). "Elevated levels of pro-inflammatory cytokines, including IL-1β, IL-6, and TNF-α, have been consistently documented in the serum and cerebrospinal fluid of patients experiencing delirium, with meta-analyses showing 2–4-fold increases compared to non-delirious patients." (PMID 41375722, 2025). "Furthermore, within the POD cohort, preoperative CSF LCN2 concentrations correlated positively with both delirium severity, as measured by the MDAS score, and levels of the proinflammatory cytokine IL-6 in the CSF." (PMID 41018204, 2025). "Persistent increases in plasma pro-inflammatory factors such as IL-6, IL-8, and MCP-1 in patients with delirium demonstrate that anti-inflammatory and pro-inflammatory cytokines are closely associated with cognitive impairment and decreased brain function after general anesthesia." (PMID 37962460, 2024). "We previously used mass-spectrometry-based plasma proteomics to define a preoperative delirium multi-protein signature that includes zinc-alpha-2-glycoprotein (AZGP1) and c-reactive protein (CRP) and a postoperative signature of interleukin-6 (IL-6), interleukin-2 (IL-2), and CRP." (PMID 39199312, 2024). "Interestingly, we conducted a meta-analysis with IL-6, TNF-α, and CRP, which were the most investigated biomarkers, and we found that they were statistically significant predictors of delirium." (PMID 37251808, 2023). "The role of IL-6/sIL-6Rα in the pathogenesis of delirium is not yet fully understood, and additional research is recommended." (PMID 37649721, 2023).
delirium (continued). "We previously demonstrated that female mice with UTIs have significantly higher plasma IL-6, increased delirium-like behaviors, and elevated neuronal CC3 compared to non-UTI control mice." (PMID 36380004, 2022). "Specifically, we found a 6-fold increase in the concentrations of IL6 in serum samples of patients with delirium (229.9 ± 105.2 pg/ml), when compared with patients without delirium (32.5 ± 9.5 pg/ml)." (PMID 36195636, 2022). "Circulating plasma proteins, including pro-inflammatory makers like C-reactive protein and IL-6, have been recently correlated with patients developing delirium after non-cardiac surgery." (PMID 31911786, 2019). "Compared to patients without delirium, delirious patients exhibited reduced release of TNFα, IP-10, IL-1β, IL-6, and IL-12 after whole blood stimulation with LPS." (PMID 29669581, 2018). "Several studies in non-ICU patients identified levels of IL-6 and IL-8 to be most strongly correlated with the development of delirium." (PMID 29801516, 2018). "We compared the strategies of using non-parametric signed rank test (delirium is the predictor and median IL-6 levels are the outcome) vs conditional logistic regression (IL-6 levels are the predictor and delirium is the outcome)." (PMID 28587598, 2017). "Several CSF cytokines increased more pronouncedly over preoperative values than in patients without delirium: IL-6 (2-fold), IL-8 (2–4-fold), and calprotectin (2–25-fold)." (PMID 27577265, 2016). "Interestingly, inflammatory mediators (for example, interleukin-1, interleukin-6, and tumor necrosis factor alpha (TNF-α)) can contribute to delirium." (PMID 25189637, 2014). "In summary, the MR analysis indicated that there may not be a causal association between delirium and the following factors: TNF-α, CRP, IL-1α, IL-1β, IL-2, IL-6, sIL-6Rα, soluble gp130, and IL-8." (PMID 37649721, 2023). "Mean IL-6 serum concentrations at hospital admission were reported in 17 studies, with a difference between the means of 24.05 pg/ml greater in patients who developed delirium than in those who did not." (PMID 37360340, 2023). "For example, one study showed increased IL-6, IL-2, and IL-1α levels in delirium due to septic shock, although no such increases in CRP, CXCL8 and TNF-α could be established." (PMID 35641947, 2022). "Third, other inflammatory markers (e.g., CRP, IL-6, or IL-8), which may have influence on delirium, were not included in our study." (PMID 34034650, 2021). "Moreover, the levels of IL-6 72 h after the operation tended to be higher in patients who developed delirium, yet this difference was not statistically significant." (PMID 34044881, 2021). "Moreover, in studies conducted among patients presented for hip surgery, differences between individuals with and without delirium were observed in plasma and cerebrospinal fluid IL-6 and IL-8 levels." (PMID 33918634, 2021). "Although the exact mechanism of the correlation of a-syn change and delirium was not clear at present, the a-syn change might just be a bystander that confounded to the increase of IL-6, a marker of systemic inflammation." (PMID 32231560, 2020). "The plasma level of IL-6, but not TNFα, was higher in patients with delirium." (PMID 29669581, 2018). "The plasma IL-6 level was higher in delirious patients compared to patients without delirium." (PMID 29669581, 2018). "In the patient with postoperative delirium, several plasma cytokines were elevated at baseline relatively to the other patients: calprotectin (5-fold elevation), MIP-1α (2-fold), MIP-1β (3-fold), and IL-6 (14-fold); these cytokines remained elevated at the later time points." (PMID 27577265, 2016). "Inflammatory markers such as IL-6, IL-2, TNF-α, and C-reactive protein have been found to be elevated in POD patients compared to those without delirium." (PMID 40092071, 2025).